DHRS2 (dehydrogenase/reductase 2)
Description:
NADPH-dependent oxidoreductase which catalyzes the reduction of dicarbonyl compounds. Displays reductase activity in vitro with 3,4-hexanedione, 2,3-heptanedione and 1-phenyl-1,2-propanedione as substrates. May function as a dicarbonyl reductase in the enzymatic inactivation of reactive carbonyls involved in covalent modification of cellular components. Also displays a minor hydroxysteroid dehydrogenase activity toward bile acids such as ursodeoxycholic acid (UDCA) and isoursodeoxycholic acid (isoUDCA), which makes it unlikely to control hormone levels. Doesn't show any activity in vitro with retinoids and sugars as substrates. Reduces proliferation, migration and invasion of cancer cells and well as the production of ROS in cancer.
Synonyms: SDR25C1; HEP27
Tractability: PROTAC: ubiquitination databases record sites on it; its protein half-life has been measured.
Gene: Protein-coding gene on chromosome 14 (23,630,115 to 23,645,639, forward strand). Ensembl gene ENSG00000100867.
Subcellular location: Mitochondrion matrix; Nucleus
Subcellular location (Human Protein Atlas): Mitochondria; Nucleoplasm
Gene Ontology:
Molecular function: carbonyl reductase (NADPH) activity; oxidoreductase activity, acting on the CH-OH group of donors, NAD or NADP as acceptor; protein binding
Biological process: cellular response to oxidative stress; electron transport chain; myeloid dendritic cell differentiation; negative regulation of apoptotic process; response to toxic substance; C21-steroid hormone metabolic process; negative regulation of cell population proliferation
Cellular component: cytoplasm; mitochondrion; nuclear envelope; nucleoplasm; nucleus; mitochondrial matrix
Genetic constraint (gnomAD): Loss-of-function variants: 29 observed, 28.24 expected, observed/expected ratio (o/e) 1.03, 90% interval 0.76 to 1.4. The upper end of that interval is the gene's LOEUF score, 1.4, which puts it in group 5 of 6, group 1 being the genes least tolerant of losing a copy. Missense variants: 439 observed, 381.97 expected, observed/expected ratio (o/e) 1.15, 90% interval 1.06 to 1.24. Synonymous variants: 164 observed, 158.38 expected, observed/expected ratio (o/e) 1.04, 90% interval 0.91 to 1.18.
Homologues: Orthologues: chimpanzee DHRS2 (97% identical), macaque DHRS2 (86% identical), dog DHRS2 (78% identical), rabbit DHRS2 (75% identical), mouse Dhrs2 (64% identical), rat Dhrs2 (64% identical), zebrafish dhrs4 (49% identical), Drosophila melanogaster Dhrs4 (48% identical), Caenorhabditis elegans dhs-13 (40% identical), tropical clawed frog MGC79752 (24% identical), Drosophila melanogaster CG31549 (24% identical), Caenorhabditis elegans Y47G6A.22 (23% identical), and 27 more. Paralogues in human: DHRS4 (59% identical), DHRS4L2 (47% identical), RDH8 (24% identical), DHRS7B (23% identical), CBR1 (22% identical), DHRS11 (22% identical), DHRS7C (22% identical), HSD11B1 (22% identical), DHRS7 (21% identical), CBR3 (20% identical), HSD11B1L (19% identical), HSDL2 (19% identical), and 1 more.
Diseases named in the same sentence as DHRS2 in open-access papers:
DHRS2 is named in the same sentence as 50 diseases in open-access papers, as found by Europe PMC text mining. Sharing a sentence is not in itself a finding about the gene and the disease. The quoted sentences say what the papers report.
breast carcinoma (8 papers, 2004 to 2024). "Conversely, genes highly expressed in PIPET_LumB, such as STC2, COX6C and DHRS2, may be associated with tumor invasion, metastasis and epithelial–mesenchymal transition in breast cancer." (PMID 38819254, 2024). "DHRS2 upregulation was associated with poor OS and DMFS in basal‐like breast cancer." (PMID 36594618, 2023). "Downregulation of COX6C and DHRS2 notably inhibited the proliferation of breast cancer cells." (PMID 36594618, 2023). "In the transwell migration assay, migrated cells transfected with shIL4I1 were remarkably decreased by 60% or more compared with control, indicating high levels of COX6C and DHRS2 could facilitate breast cancer invasion." (PMID 36594618, 2023). "To evaluate the role of COX6C and DHRS2 in breast cancer cells, we utilized short hairpin RNA (shRNA) to generate T‐47D, MDA‐MB‐231, and MCF‐7 cell lines with low COX6C or DHRS2 expression." (PMID 36594618, 2023). "Taken together, these data demonstrated that the downregulation of COX6C and DHRS2 might inhabit cell proliferation, migration, and EMT in breast cancer." (PMID 36594618, 2023).
ovarian carcinoma (5 papers, 2011 to 2023). A malignant neoplasm originating from the surface ovarian epithelium. "Another study integrated transcriptome and metabolome data and found that dehydrogenase/reductase member 2 (DHRS2) disrupts choline metabolism in ovarian cancer." (PMID 38023163, 2023). "This disruption in choline metabolism reprogramming is a primary factor behind DHRS2’s tumor-suppressive effect in ovarian cancer." (PMID 38023163, 2023). "To gain insight into the role of DHRS2 in ovarian cancer (OC), we first measured DHRS2 expression in a variety of OC cell types." (PMID 36192391, 2022). "In the present study, we have demonstrated that DHRS2 inhibits the growth and metastasis of ovarian cancer (OC) cells in vitro and in vivo." (PMID 36192391, 2022). "In ovarian cancer, HDAC inhibition likewise increased DHRS2 levels, which was linked to HDACi sensitivity." (PMID 36230614, 2022).
prostate carcinoma (4 papers, 2015 to 2024). A carcinoma that arises from epithelial cells of the prostate gland. "Our previous studies revealed that tumor-suppressive miR-145-3p was closely involved in human cancer pathogenesis by targeting oncogenes, for example, MTDH in LUSQ; MELK, NCAPG, BUB1, and CDK1 in prostate cancer; MYO1B in head and neck cancer; and MYO1B and DHRS2 in esophageal cancer." (PMID 31514295, 2019).
esophageal squamous cell carcinoma (3 papers, 2020 to 2022). Esophageal squamous cell carcinoma (ESCC) is a type of esophageal carcinoma (EC) that can affect any part of the esophagus, but is usually located in the upper or middle third. "The downregulation of DHRS2 was further related to invasion, lymph node metastasis and is associated with worse prognosis in esophageal squamous cell carcinoma." (PMID 36230614, 2022). "DHRS2 is markedly downregulated in esophageal squamous cell carcinoma (ESCC) and negatively correlates with tumor invasion, lymph node metastasis, and clinical stage." (PMID 36192391, 2022). "DHRS2 is suggested to be a tumor suppressor gene in different tumor types, including nasopharyngeal carcinoma, gastrointestinal stromal tumors, metastatic lung adenocarcinomas, esophageal squamous cell carcinoma, and renal cancer." (PMID 32586085, 2020).
colon cancer (2 papers, 2020 to 2023). "We also searched the GEO database and found that the DHRS2 gene is upregulated in colon cancer cells treated with the adenoviral LEF1 expression vector (GEO accession number: GSE3229), which is consistent with our results." (PMID 32586085, 2020).
lymph node metastasis (2 papers, 2022 to 2023). "Fisher's exact test showed the expression of both COX6C and DHRS2 are significantly related to the presence of lymph node metastasis." (PMID 36594618, 2023).
nasopharyngeal carcinoma (2 papers, 2019 to 2020). A carcinoma arising from the nasopharyngeal epithelium. "DHRS2 gene is localized in chromosome 14q11.2, a region with high-frequency heterozygous loss in many tumors, including nasopharyngeal carcinoma, gastrointestinal stromal tumors, mesothelioma, esophageal squamous cell carcinoma and metastatic lung adenocarcinomas." (PMID 31291971, 2019).
B-cell lymphoma (1 paper, 2022). "The function of both genes DHRS2 and COLCA2 in B-cell lymphoma is unknown." (PMID 36230614, 2022).
bladder cancer (1 paper, 2025). "We developed a Risk Score model that was related to the overall survival of bladder cancer patients based on doxorubicin-target HRGs: ACTG2, MYC, PDGFRB, DHRS2, and KLRD1." (PMID 38806990, 2025).
endometrial cancer (1 paper, 2022). Primary or metastatic malignant neoplasm involving the endometrium (mucous membrane that lines the endometrial cavity). "Indeed, our data suggest that its loss may significantly mitigate disease risk by reducing the expression of several proteins (ESRP1 and DHRS2) with known deleterious effects in endometrial cancer in addition to modulating cell viability and proliferative capacity." (PMID 35401936, 2022).
gastric cancer (1 paper, 2023). A primary or metastatic malignant neoplasm involving the stomach. "This analysis revealed processes active in each subclone, such as the de-regulation of CLDN18, previously reported in gastric cancer, and DHRS2, also associated with gastric carcinogenesis." (PMID 37917660, 2023).
HIV-1 infection (1 paper, 2020). The type species of lentivirus and the etiologic agent of acquired immunodeficiency syndrome (AIDS). "For example, the transcripts of DHRS2 and SEMA4D were fused to upstream LTR12D and LTR12C sequences, respectively, and upregulated upon HIV-1 infection." (PMID 33021676, 2020).
liver cancer (1 paper, 2022). An epithelial or non-epithelial malignant neoplasm that arises from the liver. "The specific BET inhibition in liver cancer cells induced an increase of DHRS2 expression in sensitive (Hep3B) and resistant cells (HepG2)." (PMID 36230614, 2022). "High DHRS2 expression was observed in BET inhibitor resistant liver cancer cell lines." (PMID 36230614, 2022).
non-small cell lung carcinoma (1 paper, 2023). A group of at least three distinct histological types of lung cancer, including non-small cell squamous cell carcinoma, adenocarcinoma, and large cell carcinoma. "DHRS2, TYMS, PLCB3, and ATP6V1D showed both TSA- and non-small-cell lung cancer (NSCLC) cell line-specific effects." (PMID 37072452, 2023).
renal cell carcinoma (1 paper, 2024). "In renal cell carcinoma, SUV4-20H2 was shown to epigenetically regulate cell proliferation through targeting of dehydrogenase/reductase 2 (DHRS2)." (PMID 38473745, 2024).
T-cell leukemia (1 paper, 2020). A malignant disease of the T-lymphocytes in the bone marrow, thymus, and/or blood. "Our results suggest that DHRS2 is one of the tumor suppressor targets of LEF1 in the Jurkat human T-cell leukemia cell line." (PMID 32586085, 2020).
type 2 diabetes (1 paper, 2019). "Through PPI and GSEA, our study found that DHRS2, ABHD10, HADH and ACLY function together in type 2 diabetes." (PMID 31088900, 2019). "Currently, there have been no reports about the function of DHRS2 in type 2 diabetes." (PMID 31088900, 2019).
cancer (16 papers, 2011 to 2023). A tumor composed of atypical neoplastic, often pleomorphic cells that invade other tissues. "DHRS2 displays closely association with the inhibition of cell proliferation, migration and quiescence in cancers." (PMID 31291971, 2019). "We further analyzed the expression of DHRS2 by using gene set enrichment analysis (GSEA) in cancer patients’ expression profiles obtained from multiple gene expression omnibus (GEO) databases." (PMID 36192391, 2022). "DHRS2 (OMIM *615194) encodes a member of the short-chain dehydrogenases/reductases that reduces proliferation, migration and invasion of cancer cells and well as the production of reactive oxygen species in cancer." (PMID 36245926, 2022). "Previous studies also found a strong up‐regulation of DHRS2 in various cancer cell lines in response to the HDACi LBH589, vorinostat, SAHA, TSA, MS‐275 and CRA‐024781.22, 23, 24 Thus, up‐regulation of DHRS2 is a common effect of HDACi treatments." (PMID 30460772, 2019). "The present study establishes mechanistic connections among metabolic enzymes, metabolites, and the malignant phenotype of cancer cells, and further develops novel pharmacological tools against OC by the induction of DHRS2 and targeting the CHKα/choline metabolic pathway." (PMID 36192391, 2022). "Furthermore, one member of the superfamily of short-chain dehydrogenases/reductases (SDR) was found to be overexpressed in cancer (DHRS2 or Hep27), SDR catalyzes the NADPH-dependent reduction of dicarbonyl compounds." (PMID 25243088, 2014). "The DHRS2 gene is located on chromosome 14q11.2, and deletion in this region occurs in a variety of cancers, suggesting that DHRS2 might play an indispensable role in the incidence and progression of cancer." (PMID 36192391, 2022). "A disseminated cancer cell cluster with high levels of oxidative phosphorylation (OXPHOS), including the upregulation of cytochrome C oxidase subunit 6C and dehydrogenase/reductase 2, is identified." (PMID 36594618, 2023). "There were no significant changes in gene expression levels for the seven other cancer genes (ABCC1, ALK1, BRCA1, DHRS2/HEP27, EGFR, ERBB2, and ERCC1)." (PMID 35743133, 2022). "The genes of CTSZ, AFF4, DHRS2, and HMGCS1 known as active agents in cancer progression, were identified as the central DEGs in the constructed PPI network in this study." (PMID 31528309, 2019). "The present study aims to establish a mechanistic connection between metabolism rewiring and alteration of cell cycle and proliferation in cancer cells, and further develop novel pharmacological tools against NPC by induction of DHRS2." (PMID 31291971, 2019). "Dehydrogenase/reductase member 2(DHRS2) belongs to the NADH/NADPH-dependent SDR family, and extensively participates in the regulation of the proliferation, migration, and chemoresistance of cancer cells." (PMID 36192391, 2022).
tumor (15 papers, 2015 to 2024). "Among risk factor genes, IL11, TRAF1, and DHRS2 were upregulated in the docetaxel-resistant group, indicating consistency with progression of tumour docetaxel resistance and poor prognosis." (PMID 38429845, 2024). "Based on these results, one may speculate that the inactivation of LEF1 may be causing the prevention of the tumor suppressor effect of DHRS2 in T cells and contributing to leukemogenesis." (PMID 32586085, 2020). "Overall, our data support that DHRS2 impairs tumor growth in vivo by the interfering with CHKα-AKT axis and choline metabolism." (PMID 36192391, 2022). "Downregulation of CHKα mediated the tumor-suppressive role of DHRS2 in OC through the interruption of choline metabolism." (PMID 36192391, 2022). "The combination of transcriptome and metabolome analyses further suggested that the interruption of choline metabolism contributed to the tumor-suppressive function of DHRS2." (PMID 36192391, 2022). "In order to explore the role of DHRS2 in tumor metastasis in vivo, we established an intraperitoneal metastatic animal model." (PMID 36192391, 2022). "Oil red O staining further illustrated that re-expression of DHRS2 resulted in a significant decrease of LD content in tumor tissues." (PMID 36192391, 2022). "The overexpression of DHRS2 leads to decreased tumor proliferation and tumor volume both in vitro and in vivo, while the DHRS2 knockdown increases it." (PMID 36230614, 2022). "DHRS2 overexpression resulted in significant reduction of tumor volume and mass." (PMID 36192391, 2022). "These actions mainly account for the tumor-suppressive role of DHRS2 in OC." (PMID 36192391, 2022). "Moreover, we assessed DHRS2 by immunohistochemistry (IHC) on the xenograft NPC tumor samples of each group." (PMID 31291971, 2019). "Reduced expression of DHRS2 has been found in various tumor tissues compared to the normal counterparts." (PMID 36192391, 2022). "Overexpression of DHRS2 resulted in reduction in tumor size and tumor mass, with no appreciable effect on mice body weight." (PMID 31291971, 2019).
DHRS2 also shares sentences with these, for which no sentence is quoted: otitis media (7 papers); Acute otitis media (5); diphtheria (3); infection (3); Middle Ear Infections (3); bronchiectasis (2); chronic obstructive pulmonary disease (2); ear infection (2); osteosarcoma (2); tetanus (2); acute lung injury (1); adenoma (1); bacteremia (1); end-stage renal disease (1); esophageal cancer (1); gastrointestinal stromal tumor (1); germ cell tumours (1); head and neck cancer (1); hematological malignancies (1); inflammation (1); interstitial lung disease (1); Lung Disease (1); parathyroid carcinoma (1); pertussis (1); pneumococcal infection (1); pneumococcal meningitis (1); pneumonia (1); renal carcinoma (1); respiratory disease (1); staphylococcus aureus infection (1).
A further 1 disease shares a sentence with DHRS2 in 1 paper.